ZEB1 (zinc finger E-box binding homeobox 1)
Diseases named in the same sentence as ZEB1 in open-access papers (continued):
Sharing a sentence is not in itself a finding about the gene and the disease.
cancer (continued). "A distinguished intracellular master regulator of EMT is zinc finger E-box binding homeobox 1 (ZEB1), a transcription factor establishing a pro-metastatic state in cancer cells." (PMID 33477794, 2021). "Most importantly, an EHF point mutation identified in cancer cells caused a loss of the capacity to inhibit ETS1-induced phenomena, including upregulation of the ZEB1/2 and EMT phenotypes." (PMID 33712555, 2021). "Many transcription factors had a main role in cancer metastasis, such as Zeb1, Twist1, Slug, and Snail1." (PMID 33923474, 2021). "Snail (SNAI1) and ZEB1 are well-known inducers of cancer EMT, and their protein abundance is transcriptionally or post-translationally regulated by many oncogenic signaling pathways, such as canonical Wnt and TGF-β." (PMID 34502497, 2021). "In this study, we show that autophagy activity increases the expression of Zeb1, consistent with literature reports on autophagy augmentation of cancer cell stemness by promoting EMT47–49, where Zeb1 also plays a role." (PMID 33468994, 2021). "Depletion of KIF13A or AP1S2 mitigates ZEB1-dependent focal adhesion dynamics, front-rear axis polarization, and cancer cell motility." (PMID 34732702, 2021). "In the same vein, Yilmaz and Christofori demonstrated that increased expression of ZEB1 decreased the response of cancer cells to therapy." (PMID 34868979, 2021). "In our studies, we found that modulation of the EMT status of cancer cells by perturbing the ZEB1/miR-200 axis led to CDK4 pathway modulation and determined the sensitivity to CDK4 inhibitors both in vitro and in vivo." (PMID 34309585, 2021). "Targeted inhibition of ZEB1 increases radiosensitivity in cancer cells through an EMT-dependent or -independent mechanism." (PMID 34217266, 2021). "Taken together, our results provide a novel insight into the metastasis of TNBC and define a promising therapeutic strategy for cancers with overactive ZEB1 by regulating the DNAJB9–FBXO45 signaling axis." (PMID 33966034, 2021). "The current study revealed that ZEB1 protein expression was higher in cancer cells than in before‐treatment cancer cells." (PMID 33764690, 2021). "ZEB1 is a well-known player in cancer, driving EMT, metastasis, and therapy resistance in many human cancers." (PMID 34884646, 2021). "It has been demonstrated that TGFβ signaling can control cancer stemness via the ZEB1 transcription factor." (PMID 34885136, 2021). "It has been demonstrated that lncRNA-ATB promotes ZEB1 and ZEB2, thereby cause EMT, attack from cancer cells, and spread of cancer." (PMID 34200243, 2021). "Zinc finger E-box-binding homeobox 1 (ZEB1) protein is a key transcriptional factor that induces epithelial–mesenchymal transition and cellular plasticity in cancer cells." (PMID 34462429, 2021). "Although miR-144 downregulated ZEB1 and ZEB2 in various types of cancers, this is the first study to investigate the interaction of ZEB1/2 and miR-144 in CRA." (PMID 34226299, 2021). "Previous studies also showed that small interfering RNA (siRNA)-mediated knockdown of ZEB1 and Snail expression can markedly increase the sensitivity of cancer cells to chemotherapy." (PMID 34208465, 2021). "ZEB1 is a transcriptional factor involved in the regulation of embryonic development and cancer progression." (PMID 34439151, 2021). "CD8+ T cells exhaustion can be triggered by molecules specifically involved in the EMT: the transcription factor ZEB1 and the micro-RNA miR-200 have been demonstrated to upregulate PD-L1 on cancer cells, thus leading to T cell suppression." (PMID 33498502, 2021). "The miR-200 family inhibits EMT, cancer growth, invasion, and metastasis via the inhibition of ZEB1 and ZEB2 (transcriptional regulators of E-Cadherin)." (PMID 34830196, 2021). "Understanding of the cellular and molecular mechanisms underpinning Zeb1-mediated regulation of stem cell self-renewal, lineage fate, and differentiation in normal and cancer stem cells remains incomplete." (PMID 33108352, 2021).
cancer (continued). "Reportedly, miR-655 is an EMT-inhibiting miRNA that targets TGFBR2 and ZEB1 at the same time in cancers." (PMID 33902589, 2021). "In HCC, a few studies reported that high ZEB1 expression was correlated with malignant tumor progression and a poor prognosis 14-16." (PMID 34234851, 2021). "Most importantly, the L285P mutation in EHF-SF abolishes its function and permits ETS1-mediated ZEB1/2 expression to promote EMT during cancer progression." (PMID 33712555, 2021). "We demonstrated that ALDH1B1 induced EMT in HT29 cells and cancer stem-like cells (through the upregulation of ZEB1), resulting in the downregulation of E-cadherin." (PMID 33419031, 2021). "ZEB1 is highly upregulated in mesenchymal-like cancer cells, which exerts transcriptional repression on p21." (PMID 34309585, 2021). "More importantly, ZEB1 protein is dynamically changed during cell cycle progression, which is negatively correlated with the sensitivity of cancer cells to chemotherapeutic treatment." (PMID 34462429, 2021). "ZEB1 can bind to the promoter of the liver cancer-derived growth factor (HDGF) and increase the level of HDGF transcription, leading to the pathogenesis of endometrial cancer (EC)." (PMID 34676171, 2021). "lncRNA-BX111887 upregulation contributes to the hypoxia-induced EMT of cancer cells by regulating expression of ZEB1 and its downstream genes E-cadherin and MMP2." (PMID 33407675, 2021). "A mouse pancreatic model also demonstrates that Zeb1 depletion reduces cancer metabolic plasticity by decreasing the basal respiration and glycolytic capacity." (PMID 33673109, 2021). "Cancer cells with a terminal mesenchymal phenotype characterized by high ZEB1, ZEB2 and SNAI1, exhibited impaired tumor-initiating capacity." (PMID 34063254, 2021). "We also identified potential transcriptional factors with known oncogenic roles in HCC, e.g. ZEB1, or in other cancer types, e.g. HES1, NR6A1, PATZ1, PAX4 and MTF1, in GE1-HCC." (PMID 33541355, 2021). "The expression of ZEB1 in cancer cells from NSCLC patients with acquired resistance to EGFR‐TKI has been previously investigated." (PMID 33764690, 2021). "Another known factor associated with conversion to the mesenchymal phenotype is ZEB1, which together with MUC1-C has been demonstrated to repress RASSF1A expression in human cancer cells." (PMID 34209669, 2021). "During the last few years, a crosstalk between the YAP cascade and EMT transcriptional factors such as ZEB1/2, Snail/Slug, and Twist has been described in several carcinomas." (PMID 34765560, 2021). "In contrast, AS906 and AS914, which derived from carcinomas with sarcomatoid features and formed loose spheroids in culture, expressed ZEB1, SNAI2, CD44, and Vimentin, but negligible levels of EpCAM and E-Cadherin (CDH1)." (PMID 33941777, 2021). "GLUT3 has been found overexpressed in mesenchymal cells of non-small cell lung cancer and ZEB1 can induce GLUT3 expression in these cancer cells, indicating that GLUT3 is an important component of EMT." (PMID 32318352, 2020). "These repressors (ZEB1/2, Snail, Slug, and Twist1/2), also known as EMT-inducing transcription factors (EMT-TF), are frequently overexpressed in cancer and associated with poor survival." (PMID 32987716, 2020). "Both treatments actually reverted the upregulation of the mesenchymal markers SNAIL1, ZEB1 as well as N-cadherin and vimentin in acidosis-adapted cancer cells." (PMID 31974393, 2020). "Previous studies have shown that CSN5 led to the metastasis and EMT activation of cancer cells through decreasing ZEB1 ubiquitination." (PMID 33162808, 2020). "An HIF-1α/Zeb1 signaling axis initiated by hypoxia has been described in several types of cancer cells." (PMID 32640738, 2020). "EMT is a complex process, showing a loss of E-cadherin expression and gain in the expression of the mesenchymal markers fibronectin, such as zinc finger E-box binding homeobox 1 (ZEB1), resulting in cancer progression and metastasis." (PMID 31793993, 2020).
cancer (continued). "Clinical trials are currently designed with cancer cell-expressed ZEB1 as a potential molecular target." (PMID 33322354, 2020). "Zeb1 and Zeb2 remarkably enhanced cancer stem cells in the head and neck in comparison with the ones in non-CSCs." (PMID 32280305, 2020). "Zinc finger E-box binding protein 1 (ZEB1) and ZEB2 are transcription activators that have frequently been associated with cancer progression." (PMID 32488850, 2020). "Accumulating evidence indicates that ZEB1 acts as a critical regulator of cancer cell proliferation and apoptosis." (PMID 32850368, 2020). "Herein, based on previous reports regarding PI3K/Akt/mTOR pathway regulating HIF-1α and HIF-1α promoting Zeb1 expression, we investigated the possible role of neddylation between HIF-1α and ZEB1 regarding cancer cell migration." (PMID 33097763, 2020). "We recently reported that LA and EPA reduced Ca2+ entry involved in Zeb1 regulation by TGFb, leading to cancer cell migration." (PMID 32640738, 2020). "On the basis of our findings, we proposed a model for PHRF1 to modulate the expression of ZEB1 and promote cancer migration and invasion." (PMID 32730336, 2020). "It was reported that overexpression of LOXL2 drove EMT via upregulating the expression of SNAIL (SNAI1/2), ZEB (ZEB1/2) via IRE1-XBP1 signaling pathway or FAK/SRC signaling pathway in cancer cells." (PMID 32211324, 2020). "Accumulating data demonstrate that ZEB1 has high expression in PCa cancer cells and is correlated with the progression and metastasis of these cancer cells." (PMID 32784981, 2020). "Taken together, these findings reveal the crucial role of ZEB1 in the phenotypic plasticity important for the dissemination of cancer cells and the establishment of metastasis in distant sites." (PMID 32266287, 2020). "Zinc finger E‐box binding homeobox 1 (ZEB1) as a transcription factor suppresses the transcription of miR‐203 in human cancer cells." (PMID 33058500, 2020). "Zinc-finger Enhancer Binding protein (ZEB1) acts as a transcription factor to promote cancer progression through regulating Epithelial to Mesenchymal Transition (EMT)." (PMID 32153739, 2020). "To further prove the role of TGF-β2 in EMT under acidic conditions, we silenced Smad2/3 and confirmed a dramatic reduction in SNAIL1 and ZEB1 in 6.5/cancer cells." (PMID 31974393, 2020). "ZEB1 expression levels, however, were dramatically induced in all three cancer cell lines under the condition of neddylation blockade." (PMID 33097763, 2020). "Expression of EMT transcription factors (e.g., TWIST, SNAIL, SLAG, ZEB1, and ZEB2), which favor migration, invasion, and metastasis, causes cancer cells to switch from an epithelial to a mesenchymal phenotype." (PMID 33371469, 2020). "The other transcription factors Slug, Twist, ZEB1 have been confirmed to serve as useful prognostic factors in many cancers." (PMID 32185181, 2020). "Zinc finger E-box binding homeobox 1 (Zeb1) has been demonstrated to participate in the acquisition of the properties of cancer stem cells (CSCs)." (PMID 33046710, 2020). "ZEB1 was abnormally expressed in several cancers and served as a target of miRNAs, affecting the development of cancers, including BC." (PMID 32408908, 2020). "Here, we report that inhibiting neddylation activates the hypoxia-inducible factor 1α (HIF-1α) through the PI3K-Akt pathway, which eventually regulates the EMT-activator ZEB1 (zinc finger E-box binding homeobox 1) in various cancer cell lines." (PMID 33097763, 2020). "Taken together, the relationship between lncRNAs and miRs in the regulation of ZEB1 in cancer cells are dynamic and complicated, and understanding these pathways is an essential part of effective cancer therapy." (PMID 32664703, 2020). "It is well-known that ZEB1 and miR-200a forms feedback loop, and the miR-200a/ZEB1 axis has been recognized as a determinant of cellular plasticity during cancer progression." (PMID 32414208, 2020).
cancer (continued). "Zinc finger E-box binding homeobox 1 (ZEB1) is the most well-characterized EMT regulator, and the miR-200 family/ZEB1 axis is recognized as a therapeutic target to prevent the progression and invasion of cancers." (PMID 32414208, 2020). "Their crosstalk though with ZEB1 or SNAIL can be relevant in an indirect way to cancer cell metabolism." (PMID 32318352, 2020). "ZEB1 has been demonstrated to be abnormally expressed in several cancers and served as a target of miRNAs." (PMID 32408908, 2020). "Enhancing the expression of miR-33b effectively inhibits Wnt/β-catenin/ZEB1 axis to suppress cancer malignancy through EMT inhibition." (PMID 32664703, 2020). "In recent decades, the understanding of the molecular mechanism of ZEB1 in cancer progression has greatly improved." (PMID 32014049, 2020). "Normally, miR-194 undergoes up-regulation to inhibit ZEB1 and subsequently, reduce the malignancy and invasion of cancer cells." (PMID 32664703, 2020). "In CRC cells, TCF4 enhances expression of ZEB1 to promote stemness and migration of cancer cells, thereby promoting chemotherapy resistance." (PMID 32664703, 2020). "As a case in point, the ZEB1 locus is subject to silencing by H3K27me3 in differentiated cancer cells and the modification is removed upon EMT-driven conversion into cancer stem cells." (PMID 33003334, 2020). "The EMT is a key process in driving cancer metastasis, with several transcription factors including Twist1, Snail, and ZEB1 cooperating to control this complex process." (PMID 32391253, 2020). "Signal transduction and activation of ZEB1 is critical to cancer transformation and epithelial-mesenchymal transition (EMT)." (PMID 33392180, 2020). "We examined the expression of EMT‐associated markers and found that the E‐cadherin expression was significantly lower in cancer tissues than in para‐cancer tissues while the expression of vimentin, Snail and ZEB‐1 was notably increased in cancer tissues." (PMID 33128348, 2020). "Down-regulation of DAXX enhanced ZEB-1 suppression of E-cadherin, leading to the enhanced proliferation and malignancy of cancer cells." (PMID 32664703, 2020). "Representative property of EMT is the functional diminution of E-cadherin, because several transcription factors such as Snail, Slug, ZEB1, and TWIST are associated with such EMT regulation during malignant tumor progression." (PMID 32376896, 2020). "Targeting of ZEB1 is considered a potential therapeutic strategy for mitigating cancer cell migration and invasion." (PMID 32850368, 2020). "Enhancing the expression of miR-200 disrupts ZEB1 expression to suppress PD-L1 and immunosuppression, resulting in decreased metastasis and invasion of cancer cells." (PMID 32664703, 2020). "Inhibition of miR-200c by CD44 contributes to ZEB1 upregulation, leading to increased migration and invasion of cancer cells and CP resistance." (PMID 32503307, 2020). "More recently, in a transgenic mouse model of ovarian carcinoma, it was demonstrated that the chemoresistance-promoting functions of TAMs require expression of Zeb1 by TAMs with the release of CCL2 by the cancer cells." (PMID 33322354, 2020). "Such involvement of ZEB1 led to the investigation of its role in cancer, which clarified transcriptional regulation of target genes and other types of epigenetic regulation involving post translational modification." (PMID 33097763, 2020). "ZEB1 is also implicated in resistance to various anticancer therapies through both EMT-dependent and EMT-independent mechanisms, depending on specific cancer and treatment type." (PMID 32266287, 2020). "The recent recognition of the regulation and functions of ZEB1 has shed new light on understanding its potential clinical and therapeutic implications in cancers." (PMID 32014049, 2020). "Among several proteolytic enzymes implicated in cancer invasion, RCP and Zeb1 increase MT1-MMP, which is critical for RCP-induced OSCC invasion." (PMID 32728068, 2020).
cancer (continued). "E2F1 is implicated in regulating Zeb1 and Zeb2 expression, which promotes EMT, and MMP9, which drives cancer cell invasion." (PMID 32224870, 2020). "An increasing number of literatures have confirmed the oncogenic function of ZEB1 in a wide range of malignant tumors, especially in PC." (PMID 32484209, 2020). "Recent studies have highlighted both radio- and chemotherapy when used alone as major factors in cancer cell plasticity, promoting in vitro invasion and migration in a ZEB1-dependent manner through the ERK1/2 signaling pathway." (PMID 32266287, 2020). "Transcription factor ZEB1 suppresses miR‐203 expression and then activates cancer cell epithelial differentiation." (PMID 33058500, 2020). "Reports have shown that ZEB1 acts as a transcriptional repressor or activator in various cancer types." (PMID 32850368, 2020). "Elevated expression of CCR2 and MMP9 in ZEB1 wildtype F4/80low macrophages provided a positive feedback loop with ZEB1 wildtype cancer cells through cancer cell-expressed CCL2 cytokines." (PMID 32283687, 2020). "GRHL2 suppresses EMT and has an expression pattern inversely correlated with that of ZEB1 in numerous cancers." (PMID 32005677, 2020). "Studies have pointed out that ZEB1 can inhibit the levels of E‐cadherin, and paticipate in the metastasis and proliferation of various cancers." (PMID 32281302, 2020). "ZEB1 and its two proteins are studied widely as they promote the epithelial–mesenchymal transition in cancer and are direct repressors of E-cadherin." (PMID 32397507, 2020). "Hsa-circ-005748 up-regulates ZEB1 by sponging miR-200c, leading to the metastasis of these cancer cells." (PMID 32664703, 2020). "Zinc Finger E-Box Binding Homeobox 1 (ZEB1) a gene that plays vital roles in the metastasis of cancer, is inhibited by microRNA-451a and a direct target of microRNA-429." (PMID 33113852, 2020). "Leva Di G. described how cancer cells, after being triggered by molecular signaling, increase their levels of ZEB1/2, which in turn decrease the expression of miR-200 and induce epithelial to mesenchymal transition." (PMID 32256980, 2020). "Cancer tissues had lower E‐cadherin and higher vimentin, Snail and ZEB‐1 expression than para‐carcinoma tissues suggesting that EMT, along with a down‐regulation of RXRα expression, was promoted in cancer tissues." (PMID 33128348, 2020). "The inhibition of EGFR expression strongly suppressed ZEB1 expression in primary carcinoma tumors and cell lines." (PMID 33396457, 2020). "These ZEB1/2-CtBP1/2 repressor complexes are important for downregulating the epithelial marker E-cadherin (CDH1) during carcinoma progression and during developmental processes such as neurulation and pituitary lactotrope differentiation." (PMID 32796736, 2020). "ZEB1-mediated epigenetic dysregulation is documented in metastatic NSCLC and a variety of cancer types, implying a causal role in disease pathogenesis." (PMID 31719531, 2019). "Increased expression of mesenchymal markers, such as ZEB1, SNAIL, and Twist1, have been shown to induce cancer EMT and to be closely associated with the generation of cancer stem cells." (PMID 31861383, 2019). "The unexpected role of hypoxia-induced ZEB1 established by our study offers additional approaches to target TAMs in cancer therapy." (PMID 31263103, 2019). "Altogether, these results suggest that stromal CAFs directly regulate the growth of PyMT-cancer cells (in a paracrine fashion), and ZEB1 deletion in stromal CAFs strongly suppressed the growth and collective invasion of cancer cells in the PyMT mouse model." (PMID 31324807, 2019). "Taken together, these data suggest that the ISL1/SETD7 complex directly binds to the ZEB1 promoter to activate its expression in gastric cells, which consequently leads to cancer tumorigenesis in GC." (PMID 30674889, 2019). "In several human cancer cell lines, the expression of ZEB1 induces EMT, as well as cancer cell invasion and metastasis." (PMID 31275381, 2019).